DKK3 (dickkopf Wnt signaling pathway inhibitor 3)
Diseases named in the same sentence as DKK3 in open-access papers (continued):
Sharing a sentence is not in itself a finding about the gene and the disease.
pancreatitis (2 papers, 2021 to 2026). Inflammation of the pancreas. "In conclusion, our current study reveals an essential role of Dkk3 during the regeneration after acute liver injury and pancreatitis, and establishes a new link between DKK3, canonical Wnt‐signaling and Hh‐signaling." (PMID 34306986, 2021). "Significantly reduced damage was further substantiated by lower collagen content, alpha smooth muscle actin staining (ACTA2), and transforming growth factor β (Tgfb1) expression in Dkk3‐null animals 96 h after pancreatitis induction, indicating less fibrosis at this time point." (PMID 34306986, 2021). "To probe the relevance of DKK3 during tissue regeneration upon damage, we analyzed DKK3 expression levels in wildtype animals with chemically induced acute or chronic liver failure (ALF, CLF) or pancreatitis." (PMID 34306986, 2021). "At 96 h after induction of pancreatitis, GSEA terms indicating proliferation (e.g., G2/M checkpoint) were enriched in Dkk3‐knockout animals, whereas wildtype animals still displayed an increased enrichment in fibrosis (e.g., EMT) and inflammation (e.g., Inflammatory response)." (PMID 34306986, 2021).
pulmonary fibrosis (2 papers, 2010 to 2023). Chronic progressive interstitial lung disorder characterized by the replacement of the lung tissue by connective tissue, leading to progressive dyspnea, respiratory failure, or right heart failure. "We found in this model that circulating levels of CXCL9, DKK3, and MMP3 were already significantly elevated in day 18 samples, on average 10 days before the diagnosis of cGVHD, including pulmonary fibrosis." (PMID 37526081, 2023).
retinal degeneration (2 papers, 2007 to 2012). Degeneration of the retina. "In response to photoreceptor death in a murine model of retinal degeneration, Dkk3 expression was upregulated, and functioned to inhibit caspase activation in Müller glia." (PMID 22355249, 2012). "We previously demonstrated that Dkk3 transcripts were increased in a mouse model of retinal degeneration, particularly during cone photoreceptor death." (PMID 18093317, 2007). "We recently demonstrated that Dkk3 transcripts are upregulated during photoreceptor death in a mouse model of retinal degeneration." (PMID 18093317, 2007).
Sepsis (2 papers, 2023 to 2025). Sepsis is defined as life-threatening organ dysfunction caused by a dysregulated host response to infection. "In a pediatric ICU cohort comprising patients with sepsis, urinary DKK3 levels upon ICU admission were independently associated with an increased risk of AKI, septic AKI, and ICU mortality." (PMID 39811377, 2025). "Further, in an unpublished proteomics analysis for early sepsis (samples taken at median day 28 after HCT) neither DKK3 nor MMP3 were detected." (PMID 37526081, 2023).
transitional cell carcinoma (2 papers, 2020 to 2022). A malignant neoplasm arising from the transitional epithelium, usually affecting the urinary bladder, ureter, or renal pelvis. "Approximately 56.1% (46 of 82) of invasive carcinoma tissues showed complete loss of DKK3; DKK3 was absent in most mucinous, serous, endometrioid, and undifferentiated carcinomas, while its expression was not reduced in transitional cell carcinoma." (PMID 35205672, 2022). "Additionally, nMMP-14 suppressed the expression of Dickkopf-3 (DKK3) in human urothelial cell carcinoma tissue, which led to increased invasiveness of cells." (PMID 33352765, 2020).
urothelial carcinoma (2 papers, 2014 to 2021). A malignant neoplasm derived from the transitional epithelium of the urinary tract (urinary bladder, ureter, urethra, or renal pelvis). "MMP-14 can transcriptionally downregulate the mRNA levels of Dickkopf-related protein-3 (DKK3) in urothelial carcinoma cells, which is secreted and regulates cell invasion by interaction with Wnt signaling." (PMID 35008569, 2021).
acute leukemia (1 paper, 2017). A clonal (malignant) hematopoietic disorder with an acute onset, affecting the bone marrow and the peripheral blood. "We measured the DKK3 mRNA expression levels in patients with acute leukemia by PCR." (PMID 28969056, 2017).
acute myeloid leukemia (1 paper, 2022). Acute myeloid leukemia (AML) is a group of neoplasms arising from precursor cells committed to the myeloid cell-line differentiation. "The prognostic value of DKK3 expression has also been reported in ovarian, renal, and thyroid cancers and in blood cancers including acute myeloid leukemia." (PMID 36497305, 2022).
adrenocortical tumors (1 paper, 2016). "The known WNT antagonist DKK3, normally expressed in the human adrenal cortex, is under-expressed in childhood adrenocortical tumors." (PMID 26963385, 2016).
amyloid (1 paper, 2024). "Studies reveal that the secreted Wnt antagonist Dickkopf-3 (DKK3) colocalizes to amyloid plaques in AD patients." (PMID 38285009, 2024).
Anxiety (1 paper, 2024). Intense feelings of nervousness, tension, or panic often arise in response to interpersonal stresses. "Knockdown of DKK3 using viral injections did not affect exploratory activity or anxiety in J20 mice." (PMID 38285009, 2024).
astrocytomas (1 paper, 2021). "Our findings on DKK1 and DKK3 show the importance of methylation in the regulation of Wnt signaling activity and also indicate pro-oncogenic effects of GSK3β on astrocytoma development and progression." (PMID 34064046, 2021). "Our findings on 50 astrocytoma samples revealed promoter methylation of DKK1 in 38% and DKK3 in 42.86% of the samples." (PMID 34064046, 2021). "In the present study, we investigated genetic and epigenetic changes and protein expression levels of negative regulators of Wnt signaling, DKK1, DKK3, and APC as well as glycogen synthase kinase 3 (GSK3β) and β-catenin in 64 human astrocytomas of grades II–IV." (PMID 34064046, 2021). "In this study, 64 astrocytoma samples of grades II–IV were analyzed for genetic and epigenetic changes as well as protein expression patterns in order to explore the roles of the Wnt pathway components, such as DKK1, DKK3, GSK3β, β-catenin, and APC in astrocytoma initiation and progression." (PMID 34064046, 2021).
autoimmune disease (1 paper, 2022). A disorder resulting from loss of function or tissue destruction of an organ or multiple organs, arising from humoral or cellular immune responses of the individual to their own tissue constituents. "Dickkopf homolog-3 (DKK3) has been suggested as a marker of tissue fibrosis in different conditions; however, its role in autoimmune diseases needs to be elucidated." (PMID 35683365, 2022).
Azoospermia (1 paper, 2013). Absence of any measurable level of sperm,whereby spermatozoa cannot be observed even after centrifugation of the semen pellet. "Mice generated from different sperm of a founder (electroporated male) displayed a range of different DKK3 expression based on the differential extent of inhibition of DKK3 mRNA and were associated with oligo or azoospermia." (PMID 23667645, 2013). "Interestingly, mouse showing more than 90% of DKK3 inhibition, whether in F1 generation or in F4 generation had azoospermia." (PMID 23667645, 2013).
bladder tumors (1 paper, 2012). "Another study demonstrated higher promoter CpG hypermethylation and lower expression of mRNA transcripts for sFRP-1, sFRP-2, sFRP-4, and sFRP-5, Dkk-3, and Wif-1 genes in bladder tumor compared with normal bladder mucosa showing an inverse correlation." (PMID 22325146, 2012). "The methylation levels of sFRP-2 and Dkk-3 were found to be significant independent predictors of bladder tumors, whereas with sFRP-1, sFRP-5, and Wif-1, a trend towards significance was found as independent predictors." (PMID 22325146, 2012).
blood pressure (1 paper, 2025). "Thus, our finding that DKK3 deficiency protects against AAA via VSMC phenotype modulation is not contradictory to high blood pressure (HBP)-associated AAA pathogenesis, uncovering a previously unrecognized DKK3 role." (PMID 40948935, 2025).
brain cancer (1 paper, 2025). A primary or metastatic malignant neoplasm affecting the brain. "Using the brain cancer gene database and an ML system, the authors performed a gene set enrichment analysis (GSEA), a network-based analysis, a survival analysis, and an in vitro drug screening assay based on DKK3 expression." (PMID 40002166, 2025).
cardiotoxicity (1 paper, 2021). Toxicity that impairs or damages the heart. "For instance, the gene expression levels of RNF181 and DKK3 were significantly decreased in both DOX- and ISO-induced cardiotoxicity models." (PMID 35222523, 2021).
Cognitive impairment (1 paper, 2024). Abnormal cognition is characterized by deficits in thinking, reasoning, or remembering. "Crucially, reducing DKK3 levels in a mouse model of Alzheimer’s restored this synaptic balance and improved memory, highlighting DKK3 as a potential driver of cognitive impairment." (PMID 38285009, 2024). "Together, our findings in humans and functional studies in mice identify DKK3 as a driver of synapse pathology and cognitive impairment in AD." (PMID 38285009, 2024).
colitis (1 paper, 2021). Inflammation of the colon. "Still similar mechanisms can be expected from intestinal injury, since DKK3 was also upregulated in the blood of humans suffering chronic inflammatory bowel disease as well as in murine experimental colitis models (not shown)." (PMID 34306986, 2021).
colon adenocarcinoma (1 paper, 2019). "For example, methylation of APC1A, CHD1, DKK3, and MYOD is associated with prognosis in colon adenocarcinoma patients." (PMID 31852837, 2019).
colorectal adenocarcinoma (1 paper, 2021). The most common type of colorectal carcinoma. "Such as, mRNA and protein level of DKK3 were downregulated in colorectal adenocarcinoma cell lines." (PMID 34124998, 2021).
coronary artery atherosclerosis (1 paper, 2024). "The current study is the first large population-based study to investigate the association of the kidney damage biomarkers KIM-1, DKK-3, osteopontin, and EGF with two indices of coronary artery atherosclerosis." (PMID 39587192, 2024).
dilatation (1 paper, 2017). "The following variables were entered into the forward selection logistic regression model as predictors associated with SPTD at <32 weeks: VDBP, TIMP-1, and DKK3 in the CVF, serum CRP, cervical dilatation, vaginal progesterone therapy, and use of corticosteroids." (PMID 28700733, 2017).
endometriosis (1 paper, 2021). The growth of functional endometrial tissue in anatomic sites outside the uterine body.
epithelial dysplasia (1 paper, 2022). "DKK3 expression would increase in the precancerous lesion, epithelial dysplasia, and it has been suggested that increased DKK3 expression occurs in the early stage of the carcinogenesis step of squamous epithelia in the head and neck region." (PMID 36376957, 2022).
gallbladder adenocarcinoma (1 paper, 2019). A carcinoma that arises from glandular epithelial cells of the gall bladder. "We observed low expression of DKK3 in gallbladder adenocarcinoma tumors and highly invasive GBC cell lines." (PMID 31737564, 2019).
gastric tumors (1 paper, 2025). "DKK 3 is part of the DKK protein family, which plays a role in the negative regulation of the Wnt signaling pathway, apparently having an antiproliferative role in gastric tumors and beyond." (PMID 41153243, 2025).
gynecological cancers (1 paper, 2023). "Serum DKK3 is an emerging diagnostic biomarker for colorectal and some gynecological cancers." (PMID 38022675, 2023).
hemorrhagic stroke (1 paper, 2024). A stroke caused by a bleed on the brain. "However, DKK3 upregulation in hemorrhagic stroke and neuropathic pain has been reported to attenuate neuroinflammation and induce microglial polarization from M1 to M2; however, the mechanism by which DKK3 induces microglial polarization is unclear." (PMID 38362904, 2024).
Infertility (1 paper, 2013). "It is reasonable to assume from our study that reduction in DKK3 causes activation of WNT/β-CATENIN activity in testis restricting maturation of Sc which leads to subfertility or infertility." (PMID 23667645, 2013). "Disruption of DKK3 expression in Sc due to natural mutation or due to induced effect (environmental or other causes) may interfere with Sc maturation leading to subfertility or infertility even if hormones and their receptors are normal." (PMID 23667645, 2013).
intracerebral hemorrhage (1 paper, 2020). A cerebrovascular disorder characterized by bleeding into one or both cerebral hemispheres including the basal ganglia and the cerebral cortex. "There is growing evidence that Dickkopf (DKK) 3 plays a key role in the adaptive anti-inflammatory and neuroprotective responses following intracerebral hemorrhage." (PMID 32331523, 2020).
invasive breast carcinoma (1 paper, 2009). A carcinoma that infiltrates the breast parenchyma. "In a recent report, we have demonstrated that DKK3 is frequently inactivated in invasive breast carcinomas by promoter methylation leading to loss of DKK3 expression." (PMID 19570204, 2009). "In addition to this, we have recently shown that the putative Wnt signaling inhibitor Dickkopf-3 (DKK3) is functionally inactivated by promoter methylation in more than 60% of tumors from patients with invasive breast cancer." (PMID 19570204, 2009).
invasive carcinoma (1 paper, 2022). A carcinoma that is not confined to the epithelium, and has spread to the surrounding stroma. "DKK3 loss occurred in 56.1% invasive carcinomas and was significantly associated with disease-free survival and chemoresistance in serous adenocarcinoma." (PMID 35205672, 2022). "DKK3 was significantly downregulated in invasive carcinoma compared to that in normal, benign, and borderline tumors." (PMID 35205672, 2022). "DKK3 expression was assessed using immunohistochemistry with tissue blocks from 82 patients with invasive carcinoma, and 15 normal, 19 benign, and 10 borderline tumors as controls." (PMID 35205672, 2022).
ischemia (1 paper, 2018). A hypoperfusion of the BLOOD through an organ or tissue caused by a PATHOLOGIC CONSTRICTION or obstruction of its BLOOD VESSELS, or an absence of BLOOD CIRCULATION. "The results displayed that the protein level of DKK3 in kidney tissues of I/R-induced rat AKI models was increased after 30 min of ischemia and 12 or 48 h of reperfusion when compared with sham group." (PMID 30180910, 2018).
Kidney Cyst (1 paper, 2024). Abnormal fluid filled sac within the kidney, either acquired or congenital. "While alterations of Wnt signaling result in multiple kidney cysts in a mouse model, another study found a potential role of genetic variations of DKK3 in ADPKD." (PMID 38186869, 2024).
leiomyoma (1 paper, 2024). A well-circumscribed benign smooth muscle neoplasm characterized by the presence of spindle cells with cigar-shaped nuclei, interlacing fascicles, and a whorled pattern. "In one study, SFRP1 was significantly upregulated in leiomyomas relative to normal adjacent myometrium while other Wnt inhibitors such as APC, DKK1, and DKK3 were significantly downregulated." (PMID 37466765, 2024).
Listeria infection (1 paper, 2022). "Next, in order to validate the function of the FoxO4/DKK3 axis in vivo, we treated WT and FoxO4-cKO mice with DKK3 and the Wnt inhibitor Wnt-C59, respectively, in the Listeria infection model." (PMID 36106640, 2022). "Furthermore, DKK3 treatment in the Listeria infection model increased bacteria burdens in the livers and spleens of FoxO4-cKO mice." (PMID 36106640, 2022).
melasma (1 paper, 2022). "Some genes related to the Wnt/β-catenin pathway showed different behavior in fibroblasts from the skin with melasma, in relation to photoexposed adjacent skin; the DKK3 inhibitory factor was down-regulated, while WNT3A was overexpressed." (PMID 35840442, 2022). "TheWNT3A, EDN3, ESR2, PTG2, MMP1, and SOD2 genes were up-regulated, whereas the COL4A1, CSF2, DKK3, COL7A1, TIMP4, CCL2, and CDH11 genes were down-regulated in melasma skin fibroblasts when compared to the ones from adjacent healthy skin." (PMID 35840442, 2022).
memory impairment (1 paper, 2024). "Our functional analyses in AD models and our studies in human samples strongly support the notion that DKK3 contributes to synapse defects and memory impairment in AD." (PMID 38285009, 2024). "Collectively, our findings identify DKK3 as a novel driver of synaptic defects and memory impairment in AD." (PMID 38285009, 2024). "In summary, our functional studies in mice together with our results obtained from human AD patients strongly support a role for DKK3 in synapse dysfunction and memory impairment in AD." (PMID 38285009, 2024).
mesothelioma (1 paper, 2021). A usually malignant and aggressive neoplasm of the mesothelium which is often associated with exposure to asbestos. "The outcome of a phase II clinical trial investigating the effect of nivolumab in combination with MTG201, a replication-incompetent adenovirus containing the gene encoding REIC/Dkk-3, which confers anti-tumour activity, for mesothelioma is yet to be unveiled (NCT04013334)." (PMID 34226685, 2021).
mucinous adenocarcinoma (1 paper, 2020). An invasive adenocarcinoma composed of malignant glandular cells which contain intracytoplasmic mucin. "In addition, Dkk3 protein expression levels were lower in tubular than in mucinous adenocarcinomas (p<0.05); similarly, they were lower in nested than in infiltrative adenocarcinomas (p<0.05)." (PMID 33425757, 2020).
nasopharyngeal carcinoma (1 paper, 2020). A carcinoma arising from the nasopharyngeal epithelium. "Dkk3 was positively associated with survival rate among patients with nasopharyngeal carcinoma." (PMID 33425757, 2020).
non-alcoholic fatty liver (1 paper, 2022). A benign form of fatty non-alcoholic fatty liver disease where the disease has not yet progressed to the inflammation of liver. "Non-alcoholic fatty liver is a chronic inflammatory liver disease that is exacerbated in liver-specific Dkk3 knockout mice and ameliorated in liver-specific Dkk3-overexpressing transgenic mice, in a mechanism that requires the MAP kinase Ask1." (PMID 36497305, 2022).
oligodendroglioma (1 paper, 2023). A well-differentiated (WHO grade II), diffusely infiltrating neuroglial tumor, typically located in the cerebral hemispheres. "We observed that there were statistically significant differences in OS according to the different expression levels of DKK3 and CTNNB1 in the LGG group excluding patients with oligodendrogliomas compared with those in the LGG group including patients with oligodendrogliomas." (PMID 37149563, 2023).
osteoporosis (1 paper, 2021). A condition of reduced bone mass, with decreased cortical thickness and a decrease in the number and size of the trabeculae of cancellous bone (but normal chemical composition), resulting in increased fracture incidence. "That indicated that Dkk3 may be related to aging-related diseases such as osteoporosis." (PMID 34326879, 2021).